IL1B (interleukin 1 beta)
Diseases named in the same sentence as IL1B in open-access papers (continued):
Sharing a sentence is not in itself a finding about the gene and the disease.
colorectal cancer (continued). "Hence, based on the artificial analysis, we detected critical genes involved in colorectal cancer, including IL-1β, IL-2, CXCL8, and FN1." (PMID 38637796, 2024). "Anti-interleukin agents may have a positive effect on colorectal cancer, considering the presence of IL-1β, IL-6, and TNF-α in this neoplasia, which was also demonstrated in this prospective study." (PMID 38137862, 2023). "Furthermore, we found that IR-enhanced LPS-stimulated IL-1β increased the malignancy of CT26 colorectal cancer cells, thereby decreasing the CT26-implanted mice." (PMID 36430236, 2022). "In addition, ESM-1 expression has been reported to be enhanced by HIF-1α in response to hypoxia in human colorectal cancer and to be mediated by NF-κB in IL-1β-induced inflammatory conditions in human chondrocytes." (PMID 36077661, 2022). "Several studies reported that IL-1β also increases the stemness of colorectal cancer cells." (PMID 36430236, 2022). "Moreover, ASC and caspase-1, as components of the inflammasome, and the downstream substrates of caspase-1; IL-1β and IL-18 were decreased in colorectal cancer cells." (PMID 34571825, 2021). "However, unlike FDC-like cells, not only p38 but also ERK mediates COX-2 induction by IL-1β in human colorectal cancer cells." (PMID 32303181, 2020). "Several studies have demonstrated that blocking IL-1β or TNF-α or using IL-17-deficient mice markedly attenuates the colonic inflammation and development of colorectal cancer 42-44, indicating that these cytokines are the key factors responsible for the local inflammation." (PMID 32550901, 2020). "Coincidently, IL-1β and IL-6 also participate in colorectal cancer." (PMID 32670290, 2020). "Moreover, mechanistic studies have established that IL-1β, IL-6, and TNFα are involved in colorectal cancer progression and that expression of these cytokines is regulated by vitamin D." (PMID 32425932, 2020). "Palmitate exposure induces the upregulation of NOD-like receptor C4 (NLRC4), a critical component of the inflammasome complex for IL-1β processing, as well as IL-1β production via TLR4 in tumor-associated macrophages (TAMs) from liver metastases of colorectal cancer." (PMID 31847240, 2019). "However, the data on the association between SNPs in the interleukin 1 beta gene (IL1B) and colorectal cancer (CRC) are conflicting." (PMID 28157220, 2017). "Our presurgical analysis shows that some cytokine levels (IL-6, IL-8, IL-1β and TNFα) were significantly higher in plasma of patients affected by colorectal cancer compared to healthy donors and these differences progressively increase in advanced tumor stages." (PMID 24040252, 2013). "Risk estimates for IL1B and PTGS2 haplotypes in relation to risk of colorectal cancer." (PMID 24194923, 2013). "In a previous study, we found that IL-1β stimulation induced IL-6 production in colorectal cancer cells, which was counteracted by IL-1RA, suggesting that IL-1RA inhibits the IL-1/IL-6 cascade in colorectal cancer cells." (PMID 20823887, 2010). "In colorectal cancer, pro-inflammatory cytokines such as interleukin-1 beta and interleukin-6 may be accountable for the overexpression of Cox-2, important in the early stage and for progression." (PMID 19356222, 2009). "Therefore, inhibition of IL-1β, IL-6, and TNF-α may help reduce inflammation associated with colorectal cancer, potentially slowing tumor growth, angiogenesis, and metastasis." (PMID 41463421, 2025). "Furthermore, palmatine inhibited the proliferation of human colorectal cancer cell lines by reducing the expression of the inflammatory cytokines IL-1a, IL1-b, and IL-8, granulocyte colony-stimulating factor, and granulocyte-macrophage colony-stimulating factor." (PMID 38732003, 2024).
colorectal cancer (continued). "Based on these data and the correlations with cytokine levels, it can be concluded that CD25, CD80, CD86, CD274 and CD279 glycoproteins combined with specific plasma levels of IL-1β, IL-2, IL-15 and TGFβ could represent potential biomarkers for colorectal cancer." (PMID 39456247, 2024). "To investigate whether NEAT1 promotes the progression of colorectal cancer by promoting an inflammatory response, we applied qRT-PCR, Western blot, and IHC assay, which showed that the expression of IL1B and caspase-1 increased in tumor tissues and cancer cells." (PMID 36213831, 2022). "On the other hand, LPS induces pro-inflammatory cytokines (such as IL-1β, IL-6, and TNF-α) in a HMGB1-dependent manner to improve colorectal cancer progression." (PMID 40495163, 2025). "IL-6, IL-1β, IL-10, IL-17, and TNF-α were selected as key mediators of inflammation and immune regulation in colorectal cancer." (PMID 41267807, 2025). "In colorectal cancer, açaí decreased myeloperoxidase (MPO) and cytokines such as tumor necrosis factor alpha (TNF-α), interleukin 1 beta (IL-1β) and interleukin 6 (IL-6), and inhibited cyclooxygenase 2 (COX-2), also reinforcing its anti-inflammatory effect." (PMID 40343252, 2025). "According to survival analysis of core genes, colorectal cancer patients with high levels of IFNG, MMP9, and IL1B expression are likely to have shorter survival times." (PMID 40868987, 2025). "The results indicate that the p-values of survival analysis for core genes IFNG, IL1B, and MMP9 are all less than 0.05, suggesting that in colorectal cancer patients, the high expression of IFNG, MMP9, and IL1B indicates a shorter survival time." (PMID 40868987, 2025). "This study investigates the association between Fusobacterium nucleatum presence and the expression of inflammation-related genes (IL6, IL1B, IL10, IL17, TNF) in tumor and matched normal tissues from Kazakhstani patients with colorectal cancer." (PMID 41267807, 2025). "In colorectal cancer, MMP2, IL1B, IFNG, and CD4 have significant infiltration relationships with many immune cells." (PMID 40868987, 2025). "Alu RNA induces epithelial-to-mesenchymal transition in colorectal cancer via NLRP3 inflammasome activation and IL-1β release." (PMID 40565315, 2025). "Activated immune cells produce chemokines and pro-inflammatory cytokines such as IL-1β and TNF-α, further exacerbating the injury of the intestinal epithelial barrier and leading to the occurrence of UC, and even the transition to colorectal cancer." (PMID 40904624, 2025). "In this study, we systematically characterized iNOS expression at both the mRNA and protein levels in the human colorectal carcinoma cell line DLD-1 following stimulation with LPS, IL-1β, and IFN-γ." (PMID 40746423, 2025). "EPHA2 was found to promote the formation of vasculogenic mimicry (VM) in colorectal cancer (CRC) via PI3K/AKT/mTOR and ERK1/2 signaling, and TNF plays a role in angiogenesis by synergistically inducing VEGF production with IL-1beta (IL1B)." (PMID 39596139, 2024). "The authors observed increased expression of IL-10 and IL-13 and decreased expression of IL-1β, IL-6, interferon gamma (IFN-γ), TNF-α, IL-12, and IGF-1 in peripheral blood mononuclear cells (PBMCs) derived from patients with colorectal cancer." (PMID 38957737, 2024). "At the tumor level, in colorectal cancer, TNF-α induces DNA instability and, by binding to its receptor, like IL-1β, activates the oncogenic signaling pathways, especially NF-kB and Wnt, proving the strong oncogenic role of this cytokine." (PMID 38137862, 2023). "This study also demonstrated that hub genes (IL1B, GSK3B, NOS3, RELA, and CDK4) were most likely to be involved in the effects of oxidative stress brought on by geniposide in the prevention of colorectal cancer." (PMID 37894904, 2023).
colorectal cancer (continued). "As far as we know, this is the first study in which serum levels of pro-inflammatory cytokines (IL-1β, IL-6, TNF-α), inflammatory markers (ESR CRP and fibrinogen), and tumor markers (CEA and CA 19.9) have been compared in colorectal cancer." (PMID 38137862, 2023). "In inflammatory bowel disease and colorectal cancer, the NLRP1 inflammasome exerts effects through IL-1β and IL-18." (PMID 37497237, 2023). "These bacterial species are known to cause an inflammatory state by altering the intestinal barrier and producing IL-1β and TMAO, which correlate with the development of colorectal cancer." (PMID 38137918, 2023). "In terms of miR-139-5p role in inflammation, overexpression of miR-139-5p was found to inhibit MMP9, MMP7, cell proliferation, and pro-inflammatory cytokines (IL-1β, IL-6, TNF-α) in colorectal cancer cell lines." (PMID 37474869, 2023). "Our PPI network analysis results showed that IL1B, GSK3B, NOS3, RELA and CDK4 were related to oxidative stress induced by geniposide against colorectal cancer." (PMID 37894904, 2023). "NLRC4-/- mice with NAFLD also had decreased TAMs and decreased IL-1β and VEGF expression, suggesting that NLRC4 plays a key role in the growth and recurrence of liver metastases in the context of both NAFLD and colorectal cancer." (PMID 37497237, 2023). "In mouse models for nonalcoholic fatty liver disease, fatty liver enhanced the expression of IL-1β and NLRC4 in metastatic tumors, which promoted TAM infiltration and M2 polarization and increased colorectal cancer liver metastasis." (PMID 35739593, 2022). "The increase of proinflammatory factors, including IL-1β, TNF-α, and IL-6, will aggravate intestinal inflammation and promote the occurrence of colorectal cancer." (PMID 34594475, 2021). "The level of IL1β mRNA expression was measured in 13 CCCL monocultures, and 11 NCFs and 15 CAFs from colorectal cancer patients." (PMID 34066976, 2021). "Finally, the activation of NLRP3 inflammasome, with consequent production of IL-1β, IL-18 and procaspase-1 activation which induces pyroptosis (i.e. a form of programmed cell death), showed an anti-tumoral effect preventing/inhibiting colorectal cancer development." (PMID 32107391, 2020). "Inhibition of TGFBR1 can block the activation of fibroblasts mediated via IL1B/TGFB1 and reduce the secretion of pro-inflammatory cytokines in colorectal cancer, which would make the cancer cells more sensitive to chemotherapy." (PMID 32582282, 2020). "Sixty percent IL-10−/− mice develop colorectal cancer; these mice have significantly increased levels of pro-inflammatory cytokines (IFN-γ, TNF-α, IL-1β, and IL-6), indicating the chronic intestinal inflammation related with the tumor growth." (PMID 32670290, 2020). "Gene expression of ALOX15 suppresses the TNF-α signaling pathway, IL-1β/NF-κB, and IL-6/STAT3, which play a major role in increasing colorectal cancer through chronic inflammation." (PMID 32986357, 2020). "We showed here higher serum levels of IL1B, IL6, CXCL8, TNFA, CCL2 and tumor levels of IL1B, IL6, CXCL8, TNFA in colorectal cancer, suggesting the involvement of these inflammatory factors in colorectal cancer." (PMID 31528237, 2019). "In other colorectal cancer cells, SW48 cells, EM treatment slightly decreased TNFα-stimulated or IL-1β-stimulated NF-κB promoter transcriptional activities in a dose-dependent manner." (PMID 28584401, 2017). "Proinflammatory cytokines (IL-1β, IL-6, IL-8, and TNF-α) are elevated in colorectal cancer (CRC), showing the presence of an active and permanent inflammatory state." (PMID 25945105, 2015). "WBE, capable of inhibiting the secretion of IL-1β, IL-6, and TNF-α in LPS-stimulated RAW 264.7 macrophages, may contribute to the attenuation of inflammation in colorectal cancer." (PMID 41463421, 2025). "Additionally, clinical data showed that plasma levels of IL-1β, IL-6, and TNF-α are significantly elevated in patients with colorectal cancer compared with healthy controls." (PMID 41463421, 2025).
colorectal cancer (continued). "Related to this, an increase in Akkermansia muciniphila following antibiotic treatment was found to elevate mRNA levels of pro-inflammatory cytokines IL-1β, IL-6 and TNF-α, promoting uncontrolled cellular proliferation and furthering colorectal cancer progression." (PMID 40520902, 2025). "Hence, the relative expression of the IL-1β, IL-2, CXCL8, and FN1 was overexpression by colorectal cancer and administration of 5-FU." (PMID 38637796, 2024). "In this study, it was shown that IL-1β, IL-6, and TNF-α are present from the early stages of colorectal cancer compared to the control group, and the levels could be used for diagnostic purposes." (PMID 38137862, 2023). "IL-R1 deficiency on neutrophils promoted colorectal carcinoma (CRC) progression, consequently, the lack of IL-1β signaling on neutrophils due to neutralization of circulating IL-1β might contribute as well to the progression of CRC65." (PMID 36611037, 2023). "A study investigating the impact of 5-FU chemotherapy on gut inflammation showed that in AOM/DSS-induced colorectal cancer model mouse treated with 5FU, significantly elevated expression of intestinal inflammatory genes was found, including TNF-α, MCP-1, NOS2, IL6, IL1-β, and FOXP3." (PMID 34337082, 2021). "Therefore, we examined 6 common cytokines (IL-1β, IL-2R, IL-6, IL-8 IL-10 and TNF-α) and found colorectal cancer derived HT29 and SW480 cells expressed IL-8 and further increased after irradiation." (PMID 31706322, 2019). "Interestingly, the kinetics of caspase-11 upregulation following LPS and IL-1β stimulation closely correlate with those of STAT1 activation, supporting the notion that indirect STAT1 activation requires caspase-11 in colorectal carcinoma cells." (PMID 30538296, 2019). "Additionally, IL-1β in combination with IL-1 receptor antagonist (IL-1RA) regulates EMT by affecting autophagy, which promotes a series of undesirable biological behaviors such as proliferation, migration, and invasion of colorectal cancer cells." (PMID 38762529, 2024). "The NLRP3 inflammasome activates IL1β, which stimulates tryptophan hydroxylase 1 (TPH1, gene coding the 5-HT biosynthesis rate-limiting enzyme) transcription to increase 5-HT production in colorectal cancer cells, forming a positive feedback loop between 5-HT and NLRP3 signaling." (PMID 38523155, 2024). "Obese people with colorectal cancer had higher levels of zonulin, TMAO and IL-1β and lower levels of IL-10 than non-obese colorectal cancer patients and healthy controls." (PMID 38137918, 2023). "The therapies developed against these studied cytokines—IL-1β, IL-6, and TNF-α—can represent alternatives to current chemotherapeutic and immunological treatments, considering the toxicity and lack of effectiveness of chemotherapy in colorectal cancer." (PMID 38137862, 2023). "However, filtrates, IPA extracts, and EA extracts of ADS024 and DSM7 did not affect proinflammatory cytokine secretion (TNFα, IL-1β, and MIP-1α) in toxin-treated human colonic explants from colorectal cancer patients." (PMID 36704560, 2022).
Parkinson disease (149 papers, 2008 to 2026). A progressive degenerative disorder of the central nervous system characterized by loss of dopamine producing neurons in the substantia nigra and the presence of Lewy bodies in the substantia nigra and locus coeruleus. "Elevated IL-1β levels in the cerebrospinal fluid and peripheral blood are linked to AD and Parkinson’s disease (PD)." (PMID 39301197, 2024). "Patients with Parkinson’s disease (PD) have increased levels of inflammasome-associated proteins, including IL-1β and caspase-1 that can cause neuroinflammation and subsequent damage to dopaminergic neurons." (PMID 37443800, 2023). "For example, a combination of air pollution and a specific IL1B variant increased the risk of Parkinson disease." (PMID 32579111, 2020). "We observed a nominally significant association of the IL1β rs1143623 C allele with the risk for Parkinson’s disease (OR = 0.59; 95%CI = 0.38–0.92, p = 0.021)." (PMID 30813952, 2019). "Rossi and Tanaka confirmed that IL-1β caused synaptic hyperexcitability in multiple sclerosis and induced Parkinson's disease." (PMID 24782908, 2014). "In the case of Parkinson’s disease, polymorphisms in Il1β are associated with exacerbated neuropathology, and IL-1β was found to increase the rates of dopamine neuron degeneration in a Parkinson’s disease mouse model." (PMID 23087690, 2012). "Thus, studies are underway to better understand the biomarker role of IL-1β associated with the inflammatory response present in neurodegenerative diseases such as AD and Parkinson’s disease." (PMID 39859545, 2025). "Indeed, diseases such as Alzheimer’s and Parkinson’s have been associated with heightened microglial activation, astrogliosis, and increased expression of TNFα, IL-1β, and IL-6." (PMID 39376599, 2024). "NLRP3 inflammasome has also been suggested to play an important role in Parkinson’s disease (PD), a neurodegenerative disease characterized by the loss of dopaminergic neurons in the substantia nigra pars compacta, where high levels of IL-1β have been detected in patients suffering from PD." (PMID 35754962, 2022). "In a Parkinson's disease mouse model, paquinimod treatment downregulated the expression of inflammatory cytokines (IL‐6, IL‐1β and TNF‐α) and suppressed the TLR4/NF‐κB signalling pathway." (PMID 41582634, 2026). "IL-1β activates the TLR2/MyD88/NF-κB pathway in Parkinson’s disease, leading to α-synuclein spreading in Parkinson’s disease (PD), multiple-system atrophy (MSA), and dementia with Lewy bodies." (PMID 40801649, 2025). "Parkinson’s Disease Questionnaire-39 scores were significantly predicted by IL-1β (β = 0.462, 95% CI: 0.201–0.723, p = 0.002) and FPG (β = 0.312, p = 0.041), accounting for 38.7% of variance." (PMID 40672460, 2025). "From our previous studies, we reported the pathological role of IL-1β in Alzheimer’s and Parkinson’s diseases as well as other neuropathological conditions." (PMID 40725140, 2025). "The overproduction of inflammatory mediators (such as TNF-α, IL-1β and NO) by microglial cells is involved in the neurodegenerative AD and Parkinson’s disease (PD), as they can damage neurons." (PMID 39376605, 2024). "In an animal model of Parkinson’s Disease, the overexpression of IL-1β in the caudate nucleus increases tyrosine hydroxylase immunoreactivity and behavioral outcome of the animals eight weeks after lesion." (PMID 38389906, 2024). "In post mortem studies of brains from Parkinson’s or Alzheimer’s patients, overexpression of IL1β and Casp1 was reported." (PMID 39330566, 2024). "Elevated levels of the pro-inflammatory cytokines detected in the brains of Parkinson’s patients have included IFNγ, IL-1β, and TNFα." (PMID 37833807, 2023). "In this context, 1 MHz FUS alone at 528 mW/cm2 reduced the protein levels of IL-1β and enhanced glial cell line-derived neurotrophic factor, a protein known for promoting the survival of dopaminergic neurons in Parkinson’s disease." (PMID 38164436, 2023).